SOX2 (SRY-box transcription factor 2)
Diseases named in the same sentence as SOX2 in open-access papers (continued):
Sharing a sentence is not in itself a finding about the gene and the disease.
squamous cell carcinoma (continued). "In squamous cell carcinomas (SCCs), the SCC-specific SE region co-occupied by TP63 and SOX2 enhances seRNA CCAT1 (colon cancer associated transcript 1) transcription, and the TP63/SOX2/CCAT1 complex promotes tumorigenesis by activating EGFR (epidermal growth factor receptor) transcription." (PMID 35461306, 2022). "They conclude that THZ1 may effectively control the proliferation and survival of SOX2-amplified squamous cell carcinoma cells through a decrease in global transcriptional activity." (PMID 36212402, 2022). "In a subsequent study, the master transcription factor SOX2, a lineage-specific oncogene for squamous cell carcinomas, was found to be overexpressed and to promote tumor associated neutrophil (TANs)-accumulation by upregulating CXCL5 (the mouse homolog of human CXCL6) expression." (PMID 33953163, 2021). "NANOG, OCT4, and SOX2 mRNA expressions have previously been shown to be significantly higher in samples of moderately and poorly differentiated compared to well-differentiated squamous cell carcinoma." (PMID 32733958, 2020). "A possible pleiotropic function of SOX2 in squamous cell carcinomas from other locations has been suggested, based on differential interactions with other important factors that could cooperatively contribute to the development and progression of these tumors." (PMID 32635524, 2020). "However, the opposite result was obtained for squamous cell carcinoma, in which lower SOX2 and NANOG expression was found in ALDHhigh cells than in ALDHlow cells." (PMID 31921651, 2019). "The acknowledged CSCs marker SOX2, was previously reported to be highly expressed and to participate in maintaining the properties of tumor-initiating cells, promoting proliferation in squamous cell carcinoma." (PMID 31230592, 2019). "However, SOX2 expression was positively correlated with squamous cell carcinomas (SCC) compared with adenocarcinomas (ADC) (pooled OR = 5.26, 95%CI:1.08–25.6, P = 0.040)." (PMID 23990933, 2013). "However, SOX2 amplification is a less common event in adenocarcinoma relative to squamous cell carcinoma." (PMID 23620753, 2013). "Despite the molecular differences and differences in the copy number changes of SOX2 in squamous cell carcinoma and adenocarcinoma, SOX2 expression is an independent predictor of prolonged survival in both squamous cell carcinoma and adenocarcinoma of the lung." (PMID 23620753, 2013). "Our findings highlight a cell-lineage gene expression pattern for the stem cell transcriptional factor SOX2 in the pathogenesis of lung SCCs and suggest a differential activation of stem cell-related pathways between squamous cell carcinomas and adenocarcinomas of the lung." (PMID 20161759, 2010). "Furthermore, SOX2 has been reported to play a central role in maintaining the oncogenic behavior of cancer cells in squamous cell carcinomas of the lung and esophagus, where both squamous differentiation and pluripotency gene markers are expressed by SOX2-driven tumors." (PMID 40541178, 2025). "For instance, TP63 and SOX2 bind to the SEs and promoter of CCAT1, driving its expression and thereby activating the oncogenic EGFR pathway in squamous cell carcinoma." (PMID 39964764, 2025). "TP63 is characteristic in squamous cell carcinomas and, if TP63 protein is combined with SOX2 it is known to promote LUSC progression and serve as super-enhancers in squamous tumors." (PMID 40223089, 2025). "Some studies have also shown that SOX2, PITX1, and Twist1, these molecules are highly expressed in tumor stem cells of squamous cell carcinoma, while their expression levels are low in normal skin tissue." (PMID 37841446, 2023). "Squamous cell carcinomas showed frequent genic amplification of CCND1 and SOX2 and/or TP63, while ERBB2, VEGFA, GATA4, and GATA6 were more commonly amplified in adenocarcinomas." (PMID 37893095, 2023).
squamous cell carcinoma (continued). "Although previous studies have shown that SOX2 is frequently amplified in squamous cell carcinoma, we found that most BRCA (88%), COAD (98%), GBM (91%), LIHC (94%) and LUAD (92%) tumors were diploid for SOX2." (PMID 37738673, 2023). "Studies have figured out that KLF4 has an oncogene effect and can inhibit tumorigenesis in squamous cell carcinoma (SCC) cells by activating SMAD signaling pathway and SOX2 expression." (PMID 32674073, 2020). "Co-amplification of SOX2 and TP63 is often observed in squamous cell carcinomas which further validate our findings." (PMID 32974170, 2020). "There was a statistically significant difference between the relative mRNA expression of SOX2 and NANOG in adenocarcinoma compared to squamous cell carcinoma." (PMID 31921651, 2019). "Invasiveness of TF-GFP (squamous cell carcinoma) cells was strongly enhanced by co-expression of BRACHYURY and SOX2." (PMID 30453543, 2018). "Some peculiar features distinguish squamous cell cancers from other tumors, particularly related to specific determinants of squamous differentiation, such as NOTCH, TP63 and SOX2." (PMID 30060526, 2018). "SOX2 is an important oncogene for squamous cell carcinomas (SCC) of the lung and other organs through SOX2 locus amplification at 3q26." (PMID 28737489, 2017). "SOX2, one of the 17 drivers, was amplified in HNSC and LUSC and has been reported as an oncogene in squamous cell carcinoma." (PMID 28719033, 2017). "Squamous cell carcinomas showed frequent genomic amplifications of CCND1 and SOX2 and/or TP63, whereas ERBB2, VEGFA and GATA4 and GATA6 were more commonly amplified in adenocarcinomas." (PMID 28052061, 2017). "A similar, but more significant increase in the number of cancer stemness genes was also found in squamous cell carcinoma patients, NANOG (p<0.01), OCT-4 (p<0.05), SOX-2 (p<0.01), C-MYC (p<0.05)." (PMID 29069808, 2017). "Lung adenocarcinoma cell line A549, squamous cell carcinoma cell line Sq-1, large cell carcinoma cell line Lu99 and small cell carcinoma cell line Lc817 were treated with TSA, and SOX2 expression and SP cells were investigated." (PMID 27418136, 2016). "Of relevance, SOX2, OCT4 and NANOG are also particularly involved in squamous cell carcinoma malignization and progression." (PMID 26203771, 2015). "The aim of this study was to investigate the expression of SOX2, a key transcription factor and livin, an apoptotic inhibitor in bladder transitional cell carcinoma (TCC) and squamous cell carcinoma (SCC)." (PMID 28983346, 2015). "Lineage-specific induction of this event yields highly aggressive tumors at ∼100% penetrance, faithfully phenocopying the diverse anatomical distribution, the poorly differentiated squamous cell carcinoma (SCC) phenotype, and molecular markers (p63, c-MYC, and SOX2) observed in human NC." (PMID 41266112, 2026). "Although SOX2 is a biomarker of interest in various squamous cell cancers and has been proposed as a valuable therapeutic target, our study suggests that SOX2-directed therapies are unlikely to be effective in NC, especially as monotherapy." (PMID 41266112, 2026). "For instance, TFs such as SOX2 and NKX2‐1 are crucial in mediating the transformation of LUAD to squamous carcinoma, while epigenetic regulators like EZH2 and LSD1 influence tumour cell differentiation and proliferation by modulating histone modifications and DNA methylation." (PMID 40847555, 2025). "SOX2, GBU4-5 and MAGE A1 accounted for the highest proportion (18.2%) of squamous carcinomas." (PMID 38773432, 2024). "SOX2 and SOX9 regulate skin tumors, including squamous cell carcinoma." (PMID 39684417, 2024). "Co-amplification of genes SOX2 and TP63 is uniquely seen in squamous cell carcinomas." (PMID 37444412, 2023).
squamous cell carcinoma (continued). "In particular, squamous cell carcinoma (SCC) specific SE regions are cooperatively occupied with TP63 and SOX2 to boost CCAT1 seRNA transcription, CCAT1/TP63/SOX2 complex is bound to SE regions of epidermal growth factor receptor (EGFR) to promote EGFR transcription." (PMID 32278350, 2020). "A previous study on the HPV-16 LCR showed that SOX2 from the same SRY-HMG-box gene family acted as a transcriptional repressor, down-regulating the expression of the HPV E6 and E7 oncoproteins in a context of squamous cell carcinomas." (PMID 29695285, 2018). "SOX2 and TERC gene amplifications are common in all squamous cell carcinomas and their detection in early stages could be crucial for early detection and more accurate prognosis." (PMID 24410919, 2014). "In conclusion, SOX2 and TERC gene amplifications are common in all squamous cell carcinomas, and their detection in early stages could be crucial for the detection and moreaccurate prognosis of OSCCs." (PMID 24410919, 2014). "However, their genomic profiling lacked diverse genetic alterations characterized in squamous cell carcinoma, such as SOX2 amplification in the squamous differentiation pathway; PIK3CA amplification in the PI3K signaling; and FGFR1 amplification in the RTK signaling pathway." (PMID 32726920, 2020).
pancreatic cancer (108 papers, 2010 to 2026). "In pancreatic cancer, high SOX2 expression levels were associated with Tgd, mast cell, and DC infiltration." (PMID 38164286, 2024). "The risk score map suggested that the pancreatic cancer group with a high level of SOX2 expression had a worse prognosis." (PMID 38164286, 2024). "Methylation analysis showed that SOX2 methylation, including at cg03827625, was significantly different between pancreatic cancer and normal tissue and was associated with a poor prognosis." (PMID 38164286, 2024). "In a previous study, SOX2-induced CSCs in cervical and pancreatic cancer have been linked to epithelial-mesenchymal transition (EMT)-related factors." (PMID 33445526, 2021). "The relevance of our findings to human cancer is reflected by the fact that high level of SOX2 protein expression is associated with a poor patient survival in a cohort of stage II pancreatic cancer patients following gemcitabine treatment." (PMID 30382189, 2019). "CSC-associated markers Bmi1 and Sox2 sufficiently enhance self-renewal and dedifferentiation and endow pancreatic cancer cells with stemness." (PMID 30486896, 2018). "Our results revealed that low-dose gemcitabine treatment (1–5 μM) for 24 h, which has a minimal killing effect on pancreatic cancer cells, induced the expression of stemness-associated molecules Bmi1 and Sox2 as well as the CSC marker CD24." (PMID 30486896, 2018). "In a preliminary study, we also found that hypoxia promotes the expression of CSC-associated markers Bmi1 and Sox2 in pancreatic cancer cells." (PMID 30486896, 2018). "Similarly, high SOX2 expression is associated with gemcitabine resistance whereas down-regulation of SOX2 sensitizes pancreatic cancer cells to gemcitabine treatment." (PMID 30382189, 2019). "The relevance of our data to pancreatic cancer was reflected by the significant association between a high SOX2 protein level with an increased risk of tumor relapse and a poor survival of pancreatic cancer patients who underwent gemcitabine-based chemotherapy." (PMID 30382189, 2019). "Interestingly, loss of miR-145 elevates Sox2 and impairs differentiation in pancreatic tumors." (PMID 25811929, 2015). "We verified the relative expression level of SOX2 in three pancreatic cancer cell lines, PANC1, MIA-PaCa-2, and PaTu-8988, by quantitative PCR and western blotting." (PMID 38164286, 2024). "O-GlcNAcylation in the S246 region can impact Sox2 transcriptional activity and regulate cellular self-renewal in pancreatic cancer; however, the role of Sox2 O-GlcNAcylation in CRC has received little study." (PMID 38473392, 2024). "In summary, we identified the potential role of SOX2 in pancreatic cancer using pan-cancer analysis and evaluated it using a combination of functional enrichment, methylation, and immune infiltration." (PMID 38164286, 2024). "Transwell assays showed that the migration and invasion abilities of Mia-PaCa2 cells were stronger than those of PANC-1 cells, suggesting that SOX2 plays a significant role in the migration and invasion of pancreatic cancer." (PMID 38164286, 2024). "At the single-cell level, SOX2 enriched DC and Mast cells mainly in malignant cells in pancreatic cancer." (PMID 38164286, 2024). "Previous studies have reported the overexpression of SOX2 promotes the accumulation of ST6Gal-I glycosyltransferase, imparting cancer stem cell characteristics in ovarian and pancreatic cancer cells." (PMID 38632255, 2024). "Calibration analysis was used to predict the relationship between the SOX2 expression level and prognosis at 1, 6, and 12 months in patients with pancreatic cancer." (PMID 38164286, 2024). "The boxplot showed that, according to the TCGA database, SOX2 was significantly highly expressed in pancreatic cancer." (PMID 38164286, 2024).
pancreatic cancer (continued). "We also confirmed the effect of SOX2 on the invasion and migration of pancreatic cancer cells using transwell and scratch assays." (PMID 38164286, 2024). "SOX2 was found to play an important role in pancreatic cancer, especially in immune infiltration, and is thus, a potential therapeutic target and biomarker." (PMID 38164286, 2024). "A receiver operating characteristic (ROC) curve was used to determine the predictive potential and it showed that SOX2 is a new potential target for the treatment of pancreatic cancer." (PMID 38164286, 2024). "Noticeably, we also observed that human pancreatic tumor tissues exhibited heterogeneous and aberrant OCT4 and SOX2 expression as compared to normal pancreas, indicating their potential role in pancreatic cancer growth and therapy resistance." (PMID 38429272, 2024). "Mechanistically, we show for the first time that NR5A2 promotes stemness in pancreatic cancer cells via enhanced expression of SOX2 (Sex-determining region Y (SRY)-Box2)." (PMID 38012687, 2023). "Stemness‐associated biomarkers like SOX2, OCT4, Nanog, and increased ALDH activity are responsible for cancer stem cell self‐renew and differentiation and correlated with poor prognosis in pancreatic cancer patients." (PMID 37409635, 2023). "In pancreatic cancer, overexpression of SOX2 induced cell proliferation and spherogenesis, promoted cancer cell dedifferentiation, and increased intracellular CD44, and ALDH expression levels." (PMID 37213675, 2023). "In breast and pancreatic cancer, indeed, the overexpression of SOX2 leads to the EMT through the repression of the epithelial genes E-CAD and Zo-1." (PMID 38096163, 2023). "Umbelliprenin also reduced pancreatic cancer cell stemness by reducing Oct4, Nanog, and Sox2 mRNA levels (p < 0.01)." (PMID 37409635, 2023). "In pancreatic cancer, overexpression of SOX2 was able to downregulate E-cadherin and upregulate Snail, which enhanced cell invasive migration." (PMID 37213675, 2023). "Umbelliprenin treatment significantly downregulated the mRNA of Oct4, Nanog, and SOX2, suggesting umbelliprenin as a putative pancreatic cancer stem cell killing drug." (PMID 37409635, 2023). "Inhibition of FGFR signaling leads to the downregulation of SOX2, which maintains the stemness of pancreatic cancer cells." (PMID 36601474, 2022). "In pancreatic cancer cells, overexpression of Sox2 not only increases the expression of ALDH1 and CD44 but also reduces the expression of epithelial marker E-cadherin through directly binding to the promoter of Snail." (PMID 35682836, 2022). "The Res inhibits NAF-1 signaling to reduce CSC features including SOX2, Oct4 and Nanog in pancreatic cancer treatment." (PMID 34769099, 2021). "Our study also indicates that the FGFR/AKT axis is not only capable of maintaining nuclear localization of SOX2, but also stabilizes the SOX2 protein through the ubiquitination modification, thus enhancing SOX2 function in pancreatic cancer cells." (PMID 32457900, 2020). "The result again proves that SOX2 knockdown leads to the down regulation of both stemness markers in pancreatic cancer." (PMID 32457900, 2020). "SOX2 knockdown in pancreatic cancer cells leads to an inhibition of cell growth, while SOX2 transfection promotes cell entry into S-phase and proliferation, and it also increases the expression levels of CSC pancreatic ALDH1, ESA, and CD44 markers." (PMID 32523653, 2020). "We describe a FGFR/AKT/SOX2 signaling axis in regulating pancreatic cancer stemness by modulating the protein level as well as cellular localization of SOX2." (PMID 32457900, 2020). "We started with pancreatic cancer CSCs (PANC-1 CSLC and PSN-1 CSLC) and determined the effect of dexamethasone on the expression of stem cell–associated markers (CD133, Sox2, Nanog, Bmi1, and Nestin) and the differentiation marker E-cadherin." (PMID 33115754, 2020). "SOX2 imparts stem cell‐like characteristics to human pancreatic cancer cells by promoting dedifferentiation." (PMID 32896929, 2020).